IL4 (interleukin 4)
Diseases named in the same sentence as IL4 in open-access papers (continued):
Sharing a sentence is not in itself a finding about the gene and the disease.
infection (continued). "The increase in the levels of IL-4 has been related to CMI anergy that develops as the infection progresses, this observation coinciding with our results of high bacillary load and positive immunostaining for IL-4 in liver and spleen." (PMID 29899533, 2018). "iNKT cells are a major source of early IL-4 release during infection, which is essential for the induction of germinal center B cells and ensuing IgG1 production." (PMID 29928278, 2018). "Thereafter, parasite-specific IgG1 and IL-4 responses are detected, indicating polarization toward a type 2 immune response as infection progresses." (PMID 28993458, 2018). "A significant increase in IFN-γ+ CD8+ lymphocytes was detected at weeks 6 and 10, and a reduction in CD8+ T cells expressing IL-4 was seen at week 10 post-infection in Treg depleted mice." (PMID 30410119, 2018). "Murine infection with the lung migrating nematode, Nippostrongylus brasiliensis, elicits a strongly polarised type 2 response, characterised by IL-4, IL-13, IL-5 and IL-9 cytokines." (PMID 30500858, 2018). "Both IFN-γ and IL-4 are required for this effect, and both the inoculation of S. mansoni eggs to the hepatic portal vein, and the infection of mice with cercariae were shown to increase innate immune cells and both Th1 and Th2 cells in the liver." (PMID 29373600, 2018). "Infected animals had significantly elevated IL-4 mRNA levels on SD 8 as compared to group C (W = 333, P < 0.001) while on SD 15 this was only seen in animals that received a single infection (χ2 = 38.702, df = 8, P = 0.039)." (PMID 29973271, 2018). "In IL-4-polarized macrophages, a further enhancement of infection was statistically significant for IL-25 alone, TSLP alone, and every combination of IL-33 with the other alarmins." (PMID 30282716, 2018). "Despite the strong inflammatory pattern, IL-1Ra and IL-4 are also induced during the acute infection." (PMID 29768624, 2018). "In our study, we only found significant difference of TNF-α response in the 2000 CFU level of infection between the two strains, same as other cytokines including IL-4, IL-10, GM-CSF, IL-1β, IL-2, IL-6, IL-13, and IL-18." (PMID 30577452, 2018). "Mice with IRF4 deficient CD11c+ cells had less secretion of IL-4, IL-15 and IL-13 after immunization with OVA and papain as well as during infection with the nematode Nippostrongylus brasiliensis." (PMID 29343807, 2018). "Increased differentiation of Th1 and Th17 cells after fbp1Δ mutant yeast infection was accompanied by decreased differentiation of IL-4 -, IL-5 -, and IL-13 -producing Th2 cells compared to H99 infection." (PMID 29317510, 2018). "Although we observed a robust production of IL-4 in CD169-DTR/wild-type chimeras by day 3 of infection, NKT cells from CD169-DTR/CD1d−/− chimeras were impaired regarding this cytokine." (PMID 29249358, 2018). "Dectin-2 is postulated to induce Th2-type responses and IL-4-dependent mucin production in the lungs following infection with C.n-D." (PMID 30131805, 2018). "Due to the pro- and anti-inflammatory properties of IL-4, the increased level of IL-4 showed a strong inflammatory response in the late stage of infection." (PMID 30002351, 2018). "In the study by Zhu and colleagues co-infection of S. japonicum with S. Typhimurium led to an exacerbated IFN-γ response but to an attenuated IL-4 response." (PMID 30487793, 2018). "Once infection with T. cruzi Colombian strain leads to lower inflammatory infiltrate in IL-4 knockout animals, we evaluated immune response quality in situ through cardiac homogenate and systemically through serum dosages." (PMID 30622430, 2018). "In mammals, goblet cell hyperplasia and increased mucus secretion mediated by Th2 immune responses (IL13 and IL4) are known mechanisms for certain parasitoses such as infections with helminth parasites Nippostrongylus brasiliensis and Trichinella spiralis." (PMID 30209326, 2018).
infection (continued). "An increased presence of IFN-γ+ and IL-17+ CD4+ T cells was seen at weeks 6 and 10 after infection, while only at the first period studied IL4+ CD4+ T cells appeared in decreased numbers." (PMID 30410119, 2018). "KSHV-infection only enhanced the efficiency of CSR in splenocytes cultured with LPS/IL-4 and in CH12F3-2 cells cultured with CIT." (PMID 30619193, 2018). "Unexpectedly it has been demonstrated that administration of recombinant IL-4 8 h after infection with L. major promotes IL-12 production by DCs in vivo." (PMID 28567039, 2017). "At this early stage of infection, anti-inflammatory Th2 cells and the inhibiting cytokine IL-4 thereby outweighed proinflammatory Th1 cells and IFN-y levels in ethanol-treated groups." (PMID 29348965, 2017). "Further analysis revealed that the ratio of IFN-γ to IL-4 significantly decreased during infection and during the recovery phase." (PMID 28577529, 2017). "Th1 cell and cytokine IL-4 also participated in the protection of DnaJ-ΔA146Ply against pneumococcus lethal infection." (PMID 28659923, 2017). "In this line, it was reported that following s.c. injection in the hind footpad of a very high dose (2 × 107) of L. major parasites, keratinocytes transiently upregulated il4 mRNA mostly within the first 16 h of infection." (PMID 29067025, 2017). "Circulating levels of TNF-α were low, whereas levels of IL-4 were significantly increased whenever infection was present." (PMID 29348965, 2017). "Four weeks after infection, the frequency of IFNγ and IL-4 producing cells was analyzed by flow cytometry at the site of infection." (PMID 29067025, 2017). "Cytokine production in vitro - Treatment with CXCL10 (100 ng/mL) in macrophages infected by L. infantum inhibited IL-4 production (significant at 24 h post-infection; p < 0.01) and IL-10 (p < 0.001) in two time periods." (PMID 28767981, 2017). "This indicates that LPS treatment of IL-4 DCs increases HTLV-1 uptake but restricts their productive infection and seems to recapitulate IFN-α DC restriction of HTLV-1." (PMID 28426803, 2017). "First, weanlings receiving IgE-bio and Sav-gC/IL-4 had a significantly lower fever peak after infection indicating the induction of partial protection from EHV-1 infection in this vaccinated group." (PMID 28045974, 2017). "Collectively, these data point to LCMV-promoting M(IL-4) cells to acquire a mixed M(LPS + IFN-γ)/M(IL-4) phenotype considering the ability to produce pro-inflammatory cytokines post-infection." (PMID 29250063, 2017). "During the first 3 days after infection, skin IL-4 mRNA expression was observed selectively in mast cells." (PMID 29067025, 2017). "TH1-cytokines (TNF-α, IFN-γ, IL-12p70) and TH2-cytokines (IL-4, IL-10, IL-13) were measured 8 weeks after initial infection." (PMID 28542175, 2017). "This suggests that HTLV-1 trafficking into acidic vesicles inhibits productive infection of IL-4 DCs." (PMID 28426803, 2017). "In contrast, triggering the activity of T helper 2 along with secretion of IL-4, IL-10 and IL-15 enhances the durability of infection." (PMID 28979355, 2017). "Following infection with L. major, early keratinocyte-derived IL-4 was suggested to contribute to Th1 cell differentiation." (PMID 29067025, 2017). "Fluke infection also upregulated IL-4 expression at 28 dpi (P = 0.0028), whereas IL-13 significantly increased at 28 dpi (P = 0.0259) and 70 dpi (P = 0.0426), peaking at 98 dpi (P < 0.0001)." (PMID 29216911, 2017). "A significant reduction in the number of Tax-expressing cells was observed among IL-4 DCs when infection was performed in the presence of AZT, confirming that Tax expression results from productive infection." (PMID 28426803, 2017). "To substantiate the contribution of limited MR accessibility to reduced infection in D3-MDMs, we sought to up-regulate MR expression by treatment with IL-4, a well-known inducer of MR expression in macrophages." (PMID 29020083, 2017).
infection (continued). "Infection of these mice with another strain of L. major (IR173) resulted in partial control of lesion size in IL-4−/− mice, while IL-4Rα−/− controlled lesion size efficiently." (PMID 29067025, 2017). "IFN-γ/IL-4 ratio decreased significantly from infection to convalescence, especially in the mixed Lactobacillus plantarum group." (PMID 28819629, 2017). "In contrast, there was an overall increase in expression of the anti-inflammatory molecules IL-4 and TGFβ during both acute and chronic phases of infection." (PMID 28165503, 2017). "In serum, IFN-γ increased slightly and IL-2 was downregulated during early days of infection, while Th2 cytokines IL-4 and IL-10 increased during the whole intestinal phase." (PMID 29163382, 2017). "In IL-4 DCs, the relative abundance of p19gag-positive cells significantly increased between 3h and 72 h post infection (p.i.), while it significantly decreased in IFN-α DCs, suggesting that IFN-α DC are not productively infected." (PMID 28426803, 2017). "Parasite load, as well as nitric oxide (NO), IL-4 and IL-10 production were assessed at 24 and 48 h after infection." (PMID 28767981, 2017). "The data showed that the IL-4 -stimulated mDCs generated an upregulated inflammatory response in the HP-PRRSV infected mDCs compared to VR-2332 infection (comparison #30)." (PMID 28727780, 2017). "A significant increase in the number of goblet cells was observed in the IL-4 KO mice by day 32 post infection compared to naïve mice." (PMID 28192541, 2017). "Our results show a correlation between partial and complete protection against infection with the local secretion of high levels of IL-4, IL-6, IL-10, and IL-17." (PMID 29312230, 2017). "As murine lymphocytes are not responsive to IL-13, this mouse model provided an invaluable tool to investigate a role for IL-4-responsive B cells during infection with L. major." (PMID 29176972, 2017). "Inguinal and popliteal LNC taken from mice 4 days after infection released low but significant (P < 0.05) levels of IL-4 in response to stimulation with SmCB1 or SmCL3 but only SmCB1 induced significant (P < 0.005) levels of IL-17 and IFN-γ." (PMID 28346516, 2017). "Our results showed the intestinal fluids of TLR2−/− mice produced significantly more IL-12 p40 and IFN-γ, while significantly less IL-4 was produced during the early stage of infection (5 dpi) compared with WT mice." (PMID 28979269, 2017). "In our study, serum IFN-γ levels were higher in the infection group compared with the control; meanwhile, the secretion of IL-4 decreased." (PMID 28819629, 2017). "Although IL-10 mRNA expression was not modulated after PBMC infection in our study or with the strain Ab4, a previous study has described a moderate increase of IL-10 and IL-4 protein expression after PBMC infection with the strains Ab4, RacL11, and NY03." (PMID 28925977, 2017). "The mRNA expressions of IFN-γ and IL-12 were upregulated at the early stage of infection, and the expression of IL-4, IL-10, and IL-13 increased during the muscle stage." (PMID 29163382, 2017). "Blocking of IL-4 at the infection site impaired IFNγ secretion by dLN T cells 7 days later and increased IL-4 secretion by dLN cells 1 week post infection." (PMID 29067025, 2017). "Our previous study revealed that IL-4 reached a peak at 7 wks post infection, then declined steadily reaching the base line by week 20 post-infection from spleen cells of S. japonicum infected mice when stimulated with the soluble egg antigens." (PMID 28614408, 2017). "As previously shown, proviral DNA was detected in IL-4 DCs exposed to viral biofilm, and its amount significantly increased during the course of infection." (PMID 28426803, 2017). "In the canarypox prime/protein boost RV144 trial, the elicitation of five-function T cells expressing CD40L, IL-2, IL-4, IFN-γ, and TNF-α or three-function T cells expressing CD40L, IL-2, and IL-4 correlated with a reduced risk of infection." (PMID 29021394, 2017).
infection (continued). "The in vivo IL-4 level also peaked at 7 wks post infection, while, IFN-γ began to decline at this time point." (PMID 28614408, 2017). "As infection progressed, a decrease in the number of goblet cells was also observed in the IL-4R KO mice compared to naïve and IL-4 KO mice." (PMID 28192541, 2017). "In the BALB/c model, numerous evidences suggest that the control of the infection not only depends on the induction of IFN-γ-mediated responses, but also on the control of IL-10 and IL-4 cytokines that are associated with pathology." (PMID 28558043, 2017). "Then, the response shifts to a predominantly Th2 response characterized by the production of IL-4 for complete clearance or resolution of infection." (PMID 28583115, 2017). "We then analyzed the modulation of il-4 mRNA expressing cells 4 and 16 h following i.d. infection with L. major, at a time when expression of il-4 mRNA by keratinocytes was reported to be the highest following subcutaneous infection in the footpad." (PMID 29067025, 2017). "LAB induce anti-inflammatory factors, such as IL-4 (Th2 cells), while decreasing the levels of enteric or serum regulatory factors in the late stages of infection." (PMID 28819629, 2017). "The IL-4, IL-6, IL-10, IL-13 levels of Th2 cells continued to increase after infection during the first 9 weeks post-infection and down-regulated thereafter." (PMID 29192177, 2017). "The level of serum cytokine interferon gamma following oral administration of the L16 strain was remarkably increased during infection, as were interleukin-4 levels during convalescence." (PMID 28577529, 2017). "Dectin-2 is postulated to oppose Th2-type responses and IL-4-dependent mucin production in the lungs following infection with a serotype D strain of C. neoformans." (PMID 28107361, 2017). "Both immature and LPS-matured IL-4 DCs were then exposed to C91-PL cells for 3 h to measure viral capture, or for 3 days to measure productive infection." (PMID 28426803, 2017). "Our data suggest that a high expression of IL-4 in isolated GR-HSCs from Lgals3-/- reinforces the immunomodulatory role of these cells, interfering with Th1/Th2 balance during the chronic phase of infection." (PMID 28231240, 2017). "Lymphokines such as interferon gamma (IFN-γ) and interleukin 4 (IL-4) stimulate B cells to produce antibodies and attract and activate immune cells such as macrophages and other lymphocytes at sites of infection (8, –, 11)." (PMID 28122790, 2017). "On the protein level, the release of IL-4 was significantly diminished in saline-treated, infected mice indicating a functional inhibition of Th2 cells after infection (right)." (PMID 29348965, 2017). "Flow cytometry analysis found that not only is the CD163+ population more prone to infection with Leishmania parasites but produces more IL-4 and TNF-α than CD163- macrophages." (PMID 28355218, 2017). "In contrast, treatment with ligands of TLR-2 or TLR-5 did not affect viral capture (lanes 2–3) but led to an increased productive infection of IL-4 DCs (lanes 2–3)." (PMID 28426803, 2017). "Our work also suggests that cells with a similar phenotype expand in the thymus during infection with T. spiralis, which drives a robust Th2/IL4 response." (PMID 28406139, 2017). "IL-4 reached its peak at 7 wks post infection; then gradually decreased but kept at high level till 12 wks after infection." (PMID 28614408, 2017). "While levels of several Th2 cytokines were elevated during the entire course of the rim101Δ mutant infection, IL-4 was the only cytokine whose level was significantly decreased during the rim101Δ mutant infection at day 14 postinfection." (PMID 28143983, 2017). "The induction of a prevalent Th2-type response, with the production of IL-4, IL-5, and IL-13, results in a less robust and less efficient reaction to the infection, clinically presenting as increased disease severity and risk for future recurrent wheezing." (PMID 29206851, 2017).
infection (continued). "To directly visualize if IL-4 expression was induced in keratinocytes following infection with L. major, we used the well characterized IL-4-GFP reporter 4get mice." (PMID 29067025, 2017). "The levels of Il4 and Il13 were elevated after infection in the NaS1 KO and wild-type mice compared to naïve mice." (PMID 28192541, 2017). "In contrast, following infection with L. major LV39 IL-4−/− mice generated with embryonic stem cells of BALB/c origin still developed progressive non-healing lesions that were comparable to those of similarly infected wild-type BALB/c mice." (PMID 29067025, 2017). "H. polygyrus is a natural gastrointestinal nematode parasite of mice inducing a strong type 2 immune response; infection leads to pronounced proliferative expansion and M(IL-4) activation of tissue resident MΦ in the peritoneal cavity." (PMID 28334040, 2017). "In C57BL/6 adult mice, IFNγ-producing CD4+ T cells were essential in the initial phases of C. parvum infection to control the severity of infection, while IL-4-producing CD4+ T cells were important to accelerate resolution of infection." (PMID 29295550, 2017). "Despite the deleterious effect of IL-4 during Leishmania infection, contrasting data have been reported in the literature regarding the role of IL-4 during infection." (PMID 28567039, 2017). "WT, IL-4/IL-13-/- mice and IL-4Rα-/- mice were infected with N. brasiliensis and, at 5 days post-infection, SP-D levels in BAL fluid and serum were quantified." (PMID 26900854, 2016). "IL-4-treated primary human macrophages produce an average of [2.58 +/- 2.07] x 104 pfu/ml (mean +/- SD) of infectious DENV 48 hours after infection with MOI 1 DENV2, strain 16681, covering a >40-fold range from 2.3–97.5 x 104 pfu/ml." (PMID 26974655, 2016). "PD-L1 knockout mouse demonstrated resistance, decrease of lesion size, as well as parasitic load and IL-4 production after infection." (PMID 27536300, 2016). "Immunity to N. brasiliensis results in enhanced host secretion of IL-4 and IL-13, with IL-13 being essential for resolution of infection." (PMID 26900854, 2016). "Both the proportion and total number of Il4-GFP+ KN2+ cells were increased 5 days following infection." (PMID 26883724, 2016). "Another study showed that a highly virulent H5N1 virus induced antiviral (IFN-α and IFN-β) and proinflammatory (IL-4, IL-6, IL-8, and IL-15) cytokine mRNA expression in the lung at 24 h post infection, which abruptly decreased within the next 8 h." (PMID 27078641, 2016). "In another diabetes model, infection with Taenia crassiceps attenuates disease in two different mouse strains and is accompanied by high levels of IL-4 and M2 macrophages." (PMID 27101372, 2016). "Cytokines typical of the immune response (IL-1β, IL-2, IFN-γ, IL-4, IL-17A) were analyzed at 2 and 28 days after infection." (PMID 27189736, 2016). "La infection showed a higher number of the IL-4-producing CD4+ T lymphocyte subset than Lb infection at 4 weeks PI; however, at 8 weeks PI, La infection showed a lower number of IL-4-producing CD4+ T-cells than Lb infection." (PMID 27073297, 2016). "LPS and IFNγ treatment leads to M1 macrophage polarization, suited for combating infection and acute inflammation, whereas IL4 treatment leads to M2 polarization." (PMID 27006955, 2016). "Exacerbation of infection was attributable to enhanced production of IL-4 by CD4+ T cells and more Th2 in the lungs." (PMID 27302755, 2016). "Studies on bile and serum of patients indicated that infection with C. sinensis correlated with Th2 type responses, emphasizing the decrease in concentration in IL-2 and an increase in IL-4." (PMID 27348302, 2016). "While females respond to infection and trauma with increased antibody production and anti-inflammatory species such as IL-4 and IL-10, inflammation itself is usually more severe in men resulting in increased mortality in males." (PMID 27220776, 2016).